IL15 (interleukin 15)
Diseases named in the same sentence as IL15 in open-access papers (continued):
Sharing a sentence is not in itself a finding about the gene and the disease.
hematological malignancies (24 papers, 2017 to 2025). "Haploidentical, IL-15-stimulated NK cells are also being tested in the setting of hematologic malignancies post-hematopoietic stem cell transplant." (PMID 38545115, 2024). "Adoptive cellular therapy (ACT) using memory-like (ML) natural killer (NK) cells, generated through overnight ex vivo activation with IL-12, IL-15, and IL-18, has shown promise for treating hematologic malignancies." (PMID 38960949, 2024). "IL-15-related therapeutic interventions: IL-15 is used in hematologic malignancies using anti-IL-15 drugs, IL-15 agonists, chimeric compounds of IL-15 and other molecules, and a combination of IL-15 with adoptive cell therapies." (PMID 37153603, 2023). "An anti-CD33 trispecific killer engager containing an IL-15 moiety has entered clinical testing against hematological malignancies (NCT03214666)." (PMID 36765035, 2023). "The cytokine interleukin-15 (IL-15) has multifaceted functions and controversial roles in the development and progression of various hematological malignancies but also has a crucial function in the cytotoxic boost against tumoral cells." (PMID 37153603, 2023). "The cytokine interleukin-15 (IL-15) is of particular interest, which has been shown to contribute to the development and progression of various hematological malignancies." (PMID 37153603, 2023). "A phase I first-in-human study of ALT-803, an IL-15 superagonist complex, was carried out in patients with hematologic malignancies who relapsed after allogeneic HSCT, resulting in an ORR of 19% with 1 CR lasting 7 months." (PMID 36613644, 2022). "Nonetheless, the antitumor capacity of IL-15 by improving NK-cell function on the hematological malignancies has also been documented." (PMID 34079795, 2021). "IL-2- and IL-15-expanded NK cells, which were previously tested in clinical trials for hematological malignancies, showed similar moderate but statistically significant increases in CD107a expression induced by AMP-B at the same concentrations." (PMID 28608807, 2017). "Raman spectroscopy combined with multi-omics techniques has broad application prospects in the diagnosis of hematological malignancies, and the identification of IL15 and PIK3CG as potential therapeutic targets also provides new ideas and directions for the treatment of these diseases." (PMID 40070829, 2025). "Overall, we document an important dependence of Sezary cell survival and proliferation on IL-15 signaling and the utility of immunodeficient humanized IL-15 mice as hosts for SS – and potentially other T and NK cell-derived hematologic malignancies – PDX model generation." (PMID 37718909, 2023). "Patients with hematological malignancies showing diminished systemic cytokine response (IFN-γ, IL-15 and CXCL10/IP-10) also had correlating but lower anti-Spike antibody levels." (PMID 38090597, 2023). "A case report has described the use of CD19-CAR-T cells with membrane-bound IL-15 for B-ALL (following CD19- and CD22-CAR-T cell therapy failure), demonstrating such IL-15-expressing CAR-T cells can be applied to hematological malignancies." (PMID 36248810, 2022). "The role of IL-7 and IL-15 in contributing to CAR-T proliferation and/or engraftment has been described extensively in hematological malignancies." (PMID 31651363, 2019). "For example, two ongoing phase I clinical trials are treating hematologic malignancies with CAR NK cells and membrane-bound IL-15 (mbIL-15), which has been shown to increase NK cell proliferation and cytotoxic function in preclinical studies in an autocrine fashion (NCT04623944, NCT05020678)." (PMID 38545115, 2024). "In contrast to vaccination of a cohort of healthy participants, patients with hematological malignancies who had a lower anti-Spike response, also had a diminished systemic cytokine response (IFN-γ, IL-15 and CXCL10/IP-10), and this correlated with the lower anti-Spike antibody levels." (PMID 38090597, 2023).
hematological malignancies (continued). "In conclusion, in patients with hematological malignancies who underwent cell therapies, the ability to acutely upregulate IFN-γ and IP-10/CXCL10 at the priming vaccination and IFN-γ, IL-15, IL-7 and IL-10 upon booster vaccination were predictive of successful Ab development." (PMID 35693807, 2022). "IL15 and some of its derivatives (i.e., NIZ985; ALT-803; Receptor-Linker-IL15, RLI) has been investigated in different clinical trials, with preliminary data suggesting its role as a single agent, or in cellular treatment approaches for solid and hematological malignancies, including CLL." (PMID 39858511, 2025). "Furthermore, IL-15’s role in combination with other NK-based therapies, such as CAR NK cells and membrane-bound IL-15 (mbIL-15), presents an exciting frontier in the treatment of hematologic malignancies." (PMID 38545115, 2024). "Although some challenges still exist, the recent success involving CD19-CAR NK cells expressing IL-15 suggests that a broader application and advancement in using “off-the-shelf” CAR NK cell products for the treatment of hematologic malignancies and solid tumors may occur in the near future." (PMID 33287875, 2020). "For example, in patients with hematological malignancies who failed to produce anti-SARS-CoV antibodies, the innate systemic response was primarily characterized by IL-8 and MIP-1α, with a significant reduction in the IFN-γ, IL-15, and IP-10/CXCL10 response." (PMID 40160814, 2025).
infectious disease (13 papers, 2010 to 2025). A disorder directly resulting from the presence and activity of a microbial, viral, or parasitic agent in humans. "Given its role in memory T cell development and persistence, IL-15 has been incorporated as a vaccine adjuvant for infectious diseases." (PMID 40723393, 2025). "Interleukin 15 is a pleiotropic cytokine involved in the inflammatory response in various infectious diseases." (PMID 36902426, 2023). "Recently, genetic adjuvants using the cytokines with the synergy of IL-21 and IL-15 have been demonstrated to induce enhanced protective immunity in animal models against infectious disease." (PMID 25192845, 2014). "Similar to adjuvants including IL-12, IL-18 and IL-15, the addition of cytokine genes combined with IL-21 and IL-15 can facilitate the efficacy of potential DNA vaccines against infectious disease." (PMID 25192845, 2014). "As role of IL-7 and IL-15 alone in mediating CD8+ T cell proliferation has been recently demonstrated in non infectious disease models, next, we determined if reduced CD8+ T cell response in anti IL-7 treated KO mice infected with T. gondii is due to defect in their proliferative ability." (PMID 20520779, 2010). "Another genetic variation of the IL15 gene, the IL15 rs3775597, was selected in our evaluation due to the relevant frequency of the G variant allele in the American population, but there is yet no study that has investigated it in infectious or non-infectious disease outcomes." (PMID 39844838, 2024). "This is the first report that demonstrates in an infectious disease model that lack of both IL-7 and IL-15 not only down-regulates the development of CD127hi subset, but also reduces the frequency of CD127hi cells expressing Bcl-2." (PMID 20520779, 2010). "Thus, type I IFNs should be added to the long list of cytokines (IL-1β, IL-4, IL-6, IL-15, IL-21) and members of the tumor necrosis factor superfamily (TNFSF) (GITR-L, 4-1BB-L, OX40-L and TNF-α) that are purported to decrease Treg suppressive function in autoimmune and infectious disease models." (PMID 29672594, 2018).
cardiovascular disease (10 papers, 2017 to 2025). "Consumption of bilberry juice by patients with an increased risk for cardiovascular disease led to decreased plasma concentrations of CRP, IL-6 and IL-15." (PMID 30307962, 2018). "Although the potential protective role of IL‐15 has been demonstrated in numerous in vitro and in vivo models of cardiovascular diseases, further studies are necessary to confirm the accurate mechanism and the most effective administration of IL‐15 activators and inhibitors in these diseases." (PMID 32406586, 2020). "For example, serum IL-15 concentration has been shown to be higher in patients with cardiovascular disease, compared to patients without the disease." (PMID 33074097, 2020).
bacterial infection (9 papers, 2011 to 2025). "Meanwhile, cytokine genes such as IL2, IL10, and IL15, associated with innate immunity against bacterial infection, mostly showed positive correlations in the GI immune-related tissues of infected animals." (PMID 38563680, 2024). "Notably, viral and bacterial infections differ in their immune profiles, with viral infections typically associated with increased IL-15 and natural killer cell activity, and bacterial infections with elevated IL-18." (PMID 40565346, 2025). "Clearly, further studies are needed to identify the cell type involved in IL-15-dependent IL-15Rα-independent early IFNγ production following bacterial infection." (PMID 34956227, 2021). "The dispensability of IL-15Rα but not IL-15 to clear low dose L. monocytogenes infection indicated that IL-15 signaling can occur independently of IL-15Rα and that this signaling plays a key role in the control of bacterial infections." (PMID 34956227, 2021). "In this study of adults with bacterial infection, IL-15 gene expression was similar in all patient groups." (PMID 21711552, 2011). "Also, the IFN-γ-producing memory CD4+ T cells induced by transient bacterial infection with Listeria monocytogenes express IL-15Rβ and are responsive to IL-15." (PMID 23028916, 2012). "As BMDMs are diverse in their phenotype, it raised the possibility that lack of IL-15 signaling, in the presence or absence of IL-15Rα, might impact the frequencies of BMDM subsets with altered susceptibility to bacterial infection." (PMID 34956227, 2021).
metabolic disease (9 papers, 2015 to 2025). A congenital disorder (due to inherited enzyme abnormality) or acquired (due to failure of a metabolically important organ) disorder resulting from an abnormal metabolic process. "Interleukin-15 (IL-15), a member of the ‘four α-helix bundle’ cytokine family, has been associated with many inflammatory and metabolic diseases." (PMID 33557944, 2021). "Metabolic disorders modeled by the HFD significantly altered the IL-15 content in muscle tissue under regular treadmill training loads only in 48-week-old mice." (PMID 34858197, 2021). "Inspired by the important roles of IL-15 in metabolic diseases, we are curious whether IL-15 is also involved in the pathophysiological process of GDM." (PMID 33557944, 2021). "Therefore, the exact role of IL-15 in metabolic diseases still remains elusive, and further studies are needed." (PMID 33557944, 2021). "As mitochondrial degeneration is widely implicated in disease, there are many potential conditions where the exercise mimicking effects of IL-15 therapy might be useful, such as in frail patients or those with metabolic disease that have a low exercise capacity." (PMID 25902870, 2015).
inflammation (6 papers, 2020 to 2025). Aberrant reaction of the microcirculation characterized by movement of fluid and leukocytes from the blood into extravascular tissues. "Our observations of IL-6 and IL-15 raise the question of whether treatment with anti-IL-6 or anti-IL-15 could be effective in a transition from musculoskeletal complaints to chronic joint inflammation." (PMID 38457608, 2024). "It is demonstrated that intestinal secretion of IL-15 could trigger NK cell-mediated small intestinal inflammation." (PMID 38106519, 2023). "Systemic inflammation in obese boys was characterized by higher expression of TNF-β (p = 0.011), IL-15 (p = 0.004), and IL-2 (p = 0.046) and significantly lower concentrations of anti-inflammatory cytokines such as IL-10 (p = 0.035) and IL-13 (p = 0.002), compared to eutrophic males." (PMID 33526854, 2021).
hematological cancer (5 papers, 2017 to 2026). "It is demonstrated that CAR-T cells secreting IL-15/IL-15Ra complex display comparable efficacy as secreting IL-15 alone with reduced adverse effects in hematological cancer." (PMID 38368374, 2024). "This is further evidenced by superior activation of both the WT1-specific CD8+ T-cell clone used in this paper and antigen-specific CD8+ T-cells from hematological cancer patients after stimulation with IL-15-transpresenting DC." (PMID 28785596, 2017).
kidney (5 papers, 2012 to 2026). "Renal vasculitis correlated with kidney PD-1, CCL1, MIF, Granzyme A, IL-15, and BAFF." (PMID 42182101, 2026). "Moreover, pretreatment of WT mice with GdCl3 diminished serum IL-15 elevation during AILI and showed a negative correlation between serum IL-15 level and liver damage extent." (PMID 23028657, 2012).
myopathy (5 papers, 2007 to 2024). A disease of the muscle in which the muscle fibers do not function properly. "In agreement with a pathogenic relevance of IL-15, previous studies have suggested a correlation of IL-15 expression levels with disease activity parameters and treatment response in inflammatory myopathies." (PMID 26646698, 2015). "Our study investigated the putative role of NKG2D – IL-15 signaling for CD8+ T cell mediated pathology in inflammatory myopathies." (PMID 26646698, 2015). "Although the natural killer cell receptor/IL-15 signaling pathway contributes to progressive inflammatory muscle destruction and myopathy, whether this molecular mechanism is essential for regulation of HF-related myopathy is not fully clear." (PMID 33520013, 2021). "Finally, acting through the regulation of adipocytokine synthesis, IL-15 indirectly modifies IR of skeletal muscles and attenuates HF-related myopathy." (PMID 33520013, 2021). "Future studies using experimental models and therapeutic interventions might unravel the underlying pathological pathways and the potential of targeting NKG2D – IL-15 signaling in inflammatory myopathies." (PMID 26646698, 2015). "This indicates the possibility that IL-15 in serum may in part be derived from skeletal muscle and may reflect activity in terms of myopathy, since IL-15 is expressed by skeletal muscles." (PMID 17784951, 2007). "Therefore, IL-15 might significantly contribute to the high frequencies of CD28null T cells in inflammatory myopathies and be a valuable therapeutic target." (PMID 26646698, 2015). "In support of the early nonatrophic SMA myopathy evidenced by morphometric studies, we found that the mRNA expression level of IL-15 did not change in the SMNΔ7 TA muscle compared to that in WT samples during the PND stage." (PMID 39596480, 2024). "Thus, IL-15 produced by human myoblasts generates highly activated, cytotoxic effector CD8+NKG2Dhigh T cells in the inflamed muscle during inflammatory myopathies thereby contributing to progressive muscle destruction." (PMID 26646698, 2015). "However, IL-15 is not only able to attract, but also to generate CD28null T cells, the predominating subset of muscle-resident CD4+ and CD8+ T cells in inflammatory myopathies." (PMID 26646698, 2015). "Thus, muscle-derived IL-15 appears to have important roles in metabolism of both the myocardium and skeletal muscles, and exercise plays a role in the interplay between WAT modification and inflammation, but its value in HF-related myopathy remains to be poorly understood." (PMID 33520013, 2021).
blood cancers (4 papers, 2018 to 2023). "Interleukin-15 (IL-15) is particularly important, as it has been associated with the progression and onset of various blood cancers." (PMID 37932837, 2023). "Various IL-15 transgenic mouse models that carry cloned IL-15 under a variety of different foreign promoters have been instrumental in understanding the role of IL-15 in immunity and blood cancers." (PMID 37153603, 2023). "We will also review therapeutic approaches for inhibiting IL-15 in blood cancers." (PMID 37153603, 2023). "In addition, membrane-bound IL-15 expressed on NK cells (mbIL-15 NK) or IL15 gene-modified NK cells have been investigated and displayed the ability to survive and proliferate without exogenous cytokines, as well as superior cytotoxicity against both hematological neoplasms and solid tumors." (PMID 32140153, 2020).
cardiac disease (2 papers, 2022). "Interestingly, TgGRK5 cardiomyocytes also showed dysregulated expression of several immune-related genes, including Cxcl11, Cxcl13, and Il-15, that have been previously associated to leukocyte migration and to cardiac dysfunction and remodeling during heart disease." (PMID 33560342, 2022).
neurological diseases (2 papers, 2021 to 2022). "Two of the lead genetic variants (rs111836296 and rs74710969) were extremely rare in Europeans and lie in or tag candidate genes (IL15 and ADAMTS12) linked to AD and other neurological disorders." (PMID 35396452, 2022).
psychiatric disorder (2 papers, 2018 to 2023). A disorder characterized by behavioral and/or psychological abnormalities, often accompanied by physical symptoms. "In addition, the overactivated inflammatory processes (such as IL-1, IL-6, IL-15, and TNFα) that observed among both OA patients and patients with psychiatric disorders implied the possibility of shared biological pathways between these two traits." (PMID 40224608, 2023). "It seems that IL-15 may have a beneficial effect on psychiatric disorders instead of a deleterious one." (PMID 30662368, 2018). "Additionally, shared etiologies were also a rational speculation, since overactivated inflammatory factors (such as IL-1, IL-6, IL-15, and TNFα) and altered immune response were observed among both OA and psychiatric disorders patients." (PMID 40224608, 2023).
respiratory disease (2 papers, 2022 to 2023). "Five individual mediators were different among the cohorts (MCP‐1, IL‐7, IL‐10, IL‐13, and IL‐15) with lower concentrations in the groups with respiratory disease, particularly COPD and CRS." (PMID 36780897, 2023).
vascular disorder (2 papers, 2007 to 2024). A general term used to describe any disease affecting blood vessels]. "For all these reasons we considered it of interest to explore the occurrence of IL-15 in the circulation of patients with early SSc, with special regard to the possible association of IL-15 with vasculopathy and fibrosis." (PMID 17784951, 2007). "We conclude that IL-15 is associated with fibrotic as well as vascular lung disease and vasculopathy in early SSc." (PMID 17784951, 2007). "We therefore investigated IL-15 in the circulation of patients with early SSc and explored possible associations of serum IL-15 with vasculopathy and fibrosis." (PMID 17784951, 2007).
digestive diseases (1 paper, 2022). "In this regard, it could be argued that the addition of IL15 could even reflect the situation within the mucosa of patients with this digestive diseases." (PMID 36439157, 2022).
muscle tissue disease (1 paper, 2015). "As low muscle AMPK activity is commonly observed in a wide range of health disorders, reduced basal or exercise-stimulated IL-15 secretion and other AMPK-dependent factors may exacerbate skin or muscle tissue disease progression." (PMID 25902870, 2015).
IL15 also shares sentences with these, for which no sentence is quoted: adenocarcinoma (5 papers); IgA nephropathy (4); viral diseases (4); babesiosis (3); chronic GVHD (3); Hepatitis (3); Salmonella Infections (3); biliary tract cancer (2); cardiac hypertrophy (2); Cirrhosis (2); degenerative disc disease (2); enteritis (2); frontotemporal dementia (2); hemorrhage (2); leishmaniasis (2); leukocytosis (2); lung disease (2); membranous glomerulonephritis (2); Merkel cell carcinoma (2); neurodegenerative disease (2); Opportunistic infection (2); pancreatic adenocarcinoma (2); respiratory failure (2); retinopathy (2); Achalasia (1); acute coronary syndrome (1); acute leukemia (1); acute liver failure (1); acute myocardial infarction (1); Addison ́s disease (1).
A further 115 diseases each share a sentence with IL15 in 1 paper.